MEGF9 (multiple EGF like domains 9)
Synonyms: EGFL5
Tractability: Antibody: UniProt predicts a signal peptide or a membrane-spanning region. PROTAC: its protein half-life has been measured.
Gene: Protein-coding gene on chromosome 9 (120,600,811 to 120,714,470, reverse strand). Ensembl gene ENSG00000106780.
Subcellular location: Membrane
Subcellular location (Human Protein Atlas): Nucleoplasm; Cytosol
Gene Ontology:
Cellular component: basement membrane; membrane
Genetic constraint (gnomAD): Loss-of-function variants: 6 observed, 42.2 expected, observed/expected ratio (o/e) 0.14, 90% interval 0.077 to 0.28. The upper end of that interval is the gene's LOEUF score, 0.28, which puts it in group 1 of 6, group 1 being the genes least tolerant of losing a copy. Missense variants: 683 observed, 690.45 expected, observed/expected ratio (o/e) 0.99, 90% interval 0.93 to 1.05. Synonymous variants: 302 observed, 276.69 expected, observed/expected ratio (o/e) 1.09, 90% interval 0.99 to 1.2.
Homologues: Orthologues: chimpanzee MEGF9 (99% identical), macaque MEGF9 (95% identical), pig MEGF9 (86% identical), rabbit MEGF9 (82% identical), mouse Megf9 (79% identical), rat Megf9 (79% identical). Paralogues in human: USH2A (29% identical), LAMA1 (21% identical), LAMA2 (20% identical), LAMB4 (20% identical), LAMB1 (19% identical), LAMB2 (19% identical), HSPG2 (18% identical), LAMA3 (18% identical), LAMA5 (18% identical), LAMC1 (17% identical), LAMC3 (15% identical), AGRN (13% identical), and 15 more.
Diseases named in the same sentence as MEGF9 in open-access papers:
MEGF9 is named in the same sentence as 17 diseases in open-access papers, as found by Europe PMC text mining. Sharing a sentence is not in itself a finding about the gene and the disease. The quoted sentences say what the papers report.
breast carcinoma (5 papers, 2013 to 2021). "In consistent with these reports, miR-125b was found to exert its anti-tumor activity via regulating ENPEP (aminopeptidase A), CK2-α (casein kinase 2 alpha), CCNJ (cyclin J) and MEGF9 (multiple EGF-like-domains 9) in breast cancer." (PMID 25605244, 2015). "To investigate the importance of ENPEP, CK2-α, CCNJ, and MEGF9 proteins in breast tumors, we studied the expression of each protein by western blot analysis in 25 breast cancer patient samples (series 3)." (PMID 24098452, 2013). "Apart from the overexpression of ENPEP, CK2-α, CCNJ, and MEGF9 in certain breast cancer patients, the potential oncogenic roles of these proteins is supported by the fact that their downregulation causes significant inhibition of cell proliferation." (PMID 24098452, 2013). "Analysis of ENPEP, CK2-α, CCNJ, and MEGF9 protein expression in breast cancer patients revealed that they were overexpressed in 56%, 40–56%, 20%, and 32% of the tumors, respectively." (PMID 24098452, 2013). "The CDK5RAP2, MEGF9, snoRNA and tumour antigen pathways identified in this study could thus potentially also play roles in human breast cancer." (PMID 27158822, 2016). "In particular, our results show that restoration of miR-125b expression or knockdown of ENPEP, CK2-α, CCNJ, or MEGF9 may provide novel approaches for the treatment of breast cancer." (PMID 24098452, 2013). "Finally, we analyzed the protein expression of ENPEP, CK2-α, CCNJ, and MEGF9 in breast cancer patients." (PMID 24098452, 2013). "In addition, correlation analysis between miR-125b levels (analyzed with qRT-PCR) and the expression of ENPEP, CK2-α, CCNJ, and MEGF9 protein was studied in 25 breast cancer patient samples (series 3)." (PMID 24098452, 2013). "In addition, studies have revealed that MEGF9 may be regulated by miR-125b, which provides a new potential molecular target for the treatment of breast cancer." (PMID 34823498, 2021). "Moreover, we found that MEGF9 protein is expressed in 32% of tumors, a finding that could have therapeutic implications in breast cancer patients as this protein is a membrane receptor whose blockage might alter the proliferative signal." (PMID 24098452, 2013). "Our data suggest that in some percentage of patients with breast cancer tumors, miR-125b downregulation consistently occurs; this involves a repression of the genes that code for ENPEP and CK2-α, and potentially MEGF9 and CCNJ." (PMID 24098452, 2013). "Furthermore, comparative studies to human breast cancer would be highly prioritised since further studies are required to understand the potential involvement of CDK5RAP2 and MEGF9 in breast cancer." (PMID 27158822, 2016).
soft tissue tumors (2 papers, 2013). "A study has suggested its possible association with cancer, demonstrating a link between a decrease in MEGF9 expression and the aggressiveness of soft tissue tumors." (PMID 24098452, 2013). "Expression of MEGF9, a transmembrane protein with multiple EGF-like domains, was associated with local aggressiveness in human soft tissue tumors." (PMID 23497166, 2013).
breast tumors (1 paper, 2013). "The aim of analyzing ENPEP, CK2-α, CCNJ, and MEGF9 expression in breast tumors was to clarify their association with miR-125b." (PMID 24098452, 2013).
COVID-19 (1 paper, 2024). A disease caused by infection with severe acute respiratory syndrome coronavirus 2. "SRPK1, CSGALNACT2, B4GALT5, MEGF9, and KLF5 have increased mRNA expression in patients with severe COVID-19 compared with mild and non-COVID-19 patients." (PMID 38262689, 2024).
Insulin resistance (1 paper, 2024). Increased resistance towards insulin, that is, diminished effectiveness of insulin in reducing blood glucose levels.
Leukoencephalopathy (1 paper, 2021). This term describes abnormality of the white matter of the cerebrum resulting from damage to the myelin sheaths of nerve cells. "Mutation of MEGF9 has been related to several disorders such as Marfan syndrome and leukoencephalopathy, and decreased expression of MEGF9 in mesenchymal tumors may be associated to tumor local invasion." (PMID 34629037, 2021).
Sepsis (1 paper, 2022). Sepsis is defined as life-threatening organ dysfunction caused by a dysregulated host response to infection. "Compared to the controls, the patients with sepsis consistently showed significant isoform switching of the FLOT2, LRG1 and MEGF9 genes." (PMID 35715539, 2022).
varicocele (1 paper, 2024). A condition characterized by the dilated tortuous veins of the spermatic cord with a marked left-sided predominance. "The expression of MEGF9 and MLLT11 increased in the varicocele model group, while the expression decreased after treatment with low, medium, and high doses of BSHXP." (PMID 39391881, 2024). "BSHXP inhibiting MEGF9 and MLLT11 may become a potential therapeutic target for alleviating varicocele and MI." (PMID 39391881, 2024).
tumor (5 papers, 2013 to 2021). "In its tumor-suppressive functions, miR-125b has been reported to target ENPEP, CK2-α, CCNJ, MEGF9 or the proto-oncogene ETS1." (PMID 25633049, 2015). "miR-125b was found to perform its tumor suppressor function via the direct targeting of the 3’-UTRs of ENPEP, CK2-α, CCNJ, and MEGF9 mRNAs." (PMID 24098452, 2013). "MEGF9 was not expressed in any patient in normal breast tissue but was detected in the corresponding tumor samples by western blot analysis." (PMID 24098452, 2013).
cancer (2 papers, 2013 to 2016). A tumor composed of atypical neoplastic, often pleomorphic cells that invade other tissues. "This region spans the CDK5RAP2 (CDK5 Regulatory Subunit Associated Protein 2) and parts of the MEGF9 (Multiple Epidermal Growth Factor-Like Domains Protein 9) gene, both with previous connections to cancer." (PMID 27158822, 2016). "The relevance of ENPEP, CK2-α, CCNJ, and MEGF9 proteins in cancer is gradually being revealed." (PMID 24098452, 2013).
nervous system disorder (1 paper, 2024). A non-neoplastic or neoplastic disorder that affects the brain, spinal cord, or peripheral nerves. "Two other genes, AGAP1 and MEGF9, with QVs in six patients each, currently lack nervous system-related information in OMIM, Reactome, and GO, but recent articles have provided additional insight into the role of AGAP1 and MEGF9 in nervous system disorders." (PMID 39329968, 2024).
MEGF9 also shares sentences with these, for which no sentence is quoted: glioblastoma (1 paper); male infertility (1); Marfan syndrome (1); mesenchymal tumors (1); Obesity (1); osteoarthritis (1).